RN7SKP284 (RN7SK pseudogene 284)
Gene: Miscellaneous RNA gene on chromosome 3 (86,362,132 to 86,362,474, forward strand). Ensembl gene ENSG00000222934.
Homologues: Orthologues: chimpanzee 7SK (97% identical), mouse Gm54530 (54% identical), guinea pig 7SK (52% identical), mouse Gm56295 (49% identical). Paralogues in human: 7SK (65% identical), RN7SKP62 (63% identical), RN7SKP78 (63% identical), RN7SKP160 (63% identical), RN7SKP174 (62% identical), RN7SKP189 (62% identical), RN7SKP124 (62% identical), RN7SKP184 (62% identical), RN7SKP217 (62% identical), RN7SKP245 (62% identical), RN7SKP246 (62% identical), RN7SKP120 (62% identical), and 284 more.